BRAF (B-Raf proto-oncogene, serine/threonine kinase)
Diseases named in the same sentence as BRAF in open-access papers (continued):
Sharing a sentence is not in itself a finding about the gene and the disease.
tumor (continued). "In particular we discuss the mutant BRAF inhibitors Vemurafenib and Dabrafenib, which markedly inhibit tumor growth and advance patients’ overall survival." (PMID 23515890, 2013). "In the current study all 45 KRAS positive samples were wild-type for BRAFV600E mutation and all 12 BRAF positive samples were wild-type for KRAS, supporting the mutual exclusiveness of the two genes in the tumour process." (PMID 23536897, 2013). "We matched the BRAF results with the position of the serial tissue sections, to check for possible tumour heterogeneity." (PMID 24119386, 2013). "In our analyses, we have compared the survival of BRAF/KRAS-mutated population with that of the double-wild type population, while controlling for several other parameters (tumor site, T and N stage, grade and MSI status)." (PMID 24073892, 2013). "We have found 100% stability for BRAF status between different metastases in the same patient (n = 37) and observed an inter-tumor concordance of 90.9% between primary and paired-metastatic sites (n = 88), with only 4 discordant patients (4.0% patients)." (PMID 23976959, 2013). "For example, the cobas BRAF test only requires 5% tumor, whereas other assays specify a minimum of 30% tumor or specify that specimens with tumor content below 50% should be macrodissected." (PMID 24236296, 2013). "BRAFp.V600E tumors unequivocally showed elevated MEIS1 methylation levels when compared to BRAF wild types which showed an approximately equal extent of methylation in both tumor and paired normal colon tissue." (PMID 24244575, 2013). "We performed BRAF V600E IHC in 46 cases, of which 37 (80%) cases had sufficient tumor tissue for molecular analysis." (PMID 24252190, 2013). "This study observed that in KRAS wild-type patients, the objective response to anti-EGFR therapy was 0% in BRAF mutant tumours versus 36.3% in BRAF wild-type tumours." (PMID 23356214, 2013). "At the tumour level, somatic mutations in EGFR, KRAS, BRAF, PTEN and PIK3CA are associated with poor response to anti-EGFR therapy in CRC." (PMID 24152305, 2013). "The highest frequencies of BRAF V600E mutation in primary CNS neoplasms have been reported in PXA (up to 60-65%), a WHO grade II tumor, with 30% recurrence and 80% overall survival rates at five years following primary resection." (PMID 24252190, 2013). "Tumours with a dMMR were characterized by lower degrees of activation of CTNNB1 (p = 0.02) and the presence of c.1799 T > A mutation in the BRAF gene (p = 0.05)." (PMID 23446022, 2013). "We have identified a BRAF inhibitor, dabrafenib, and here characterize its preclinical activity with high potency, selectivity, and inhibition of human tumor xenograft growth." (PMID 23844038, 2013). "This group also demonstrated a significant difference in response rate between BRAF mutant and wild-type tumours." (PMID 23356214, 2013). "We also found that in tumour 29 T, although it was BRAF mutant and microsatellite unstable, there were low levels of methylation, in contrast to other studies." (PMID 23096130, 2013). "The manufacturers of both the Therascreen KRAS and Cobas KRAS and BRAF assays state that less than 5% mutant DNA can be detected using 100 ng gDNA isolated from FFPE tissue samples with at least 10% tumor cells on the slide." (PMID 23991070, 2013). "The MEIS1 promoter methylation status was determined by MSP, and analyzed in relation to BRAF mutation status, MSI status, and tumor location." (PMID 24244575, 2013). "KIAA1549:BRAF fusions were analyzed in the LGG cohort and we found the gene fusion slightly more frequent in infratentorial (38.5%) versus supratentorial (25%) tumours, while we didn’t note any difference for BRAF V600E mutation." (PMID 23947815, 2013).
tumor (continued). "In this paper, we described the development and analytical validation of a custom designed, multiplexed mutation assay to detect 35 mutations of interest in KRAS, BRAF, and NRAS genes in FFPE tumor tissue for patient stratification in clinical trials." (PMID 23991070, 2013). "Treatment with dabrafenib, which targets BRAF directly, resulted in tumor regression after 6 weeks, and continued decreasing in size until week 24, followed by a plateau and then progression at 8 months." (PMID 23470635, 2013). "Mutations were detected in 72 (31.9%) tumours for KRAS, in 6 (2.65%) for BRAF, in 7 (3.1%) for NRAS and in 37 (16.4%) for PIK3CA." (PMID 23374602, 2013). "Recent experience with BRAF inhibitors has suggested that a very high level of pathway inhibition (>90%) is necessary in order to achieve clinical tumor shrinkage." (PMID 23228035, 2012). "Tumoral and metastatic samples were screened for KRAS codon 12 and 13 and BRAF mutations by SNaPshot and/or direct sequencing." (PMID 23136868, 2012). "We retrospectively analyzed objective tumor response rate, (ORR) progression-free (PFS) and overall survival (OS) with respect to the mutational status of KRAS, BRAF, PIK3CA and PTEN expression in mCRC patients treated with a cetuximab-based regimen." (PMID 22569004, 2012). "The better sensitivity of the MS-PCR to detect the mutant BRAFV600E allele was not due to the presence of contaminating normal tissue, suggesting that the tumor was comprised of subclones of differing BRAF genotypes." (PMID 22235286, 2012). "In a recent published phase I trial, Dabrafenib, inhibitor of BRAF kinase for BRAF mutant, had showed its anti-tumor activity in 14 patients with BRAF mutant PTC." (PMID 23320248, 2012). "In comparison, sequencing of BRAF in short-term cultures from the same tumor revealed an easily detected mutant peak, suggesting that more than half of the tumor was comprised of BRAF mutant cells." (PMID 22235286, 2012). "In the BRAF mutant model, the combination resulted in tumor regressions at Day 19 with tumor volumes that were lower than those achieved with either drug alone (p-value = 0.008 for the comparison of the combination to either AZD8055 or selumetinib alone)." (PMID 22808163, 2012). "BRAF, NRAS and MET mutations were detected in 5 (50%), 3 (30%) and 1 (10%) of 10 FFPE tumor specimens, respectively, and 3 (20%), 2 (13.3%) and 2 (13.3%) of 15 cpDNA samples, respectively." (PMID 23144797, 2012). "A potentially synergistic relationship between BRAF mutation, CIN and tumour progression requires further investigation." (PMID 23110075, 2012). "Ultimately, in vitro measurement of apoptosis correlated better than cell viability to in vivo effectiveness as tumor regressions were observed only in the BRAF mutant xenograft model." (PMID 22808163, 2012). "Specifically, KRAS, BRAF and PIK3CA mutations were detected in 10 (45%), 3 (14%) and 2 (9%) tumor specimens, respectively." (PMID 23144797, 2012). "We also observed high detection concordance for critical ‘hot-spot’ mutations (KRAS, BRAF, PIK3CA) in matched cpDNA and archival tumor tissue, and important differences between archival tumor and cpDNA." (PMID 23144797, 2012). "Expression levels were correlated with CIN and with disease-free survival, correcting for microsatellite instability, BRAF/KRAS mutation status, Dukes stage, chemo/radiotherapy, age, gender and tumour location." (PMID 23154512, 2012). "In particular, the drug has demonstrated an antiproliferative activity against multiple BRAF mutant tumour cell lines and achieved biomarker suppression and tumour regression in BRAF mutant xenograft models." (PMID 23031422, 2012).
tumor (continued). "BRAF binds to and is downstream from the main effectors of KRAS, whose activating mutations are believed to support the chaotic tumor vascularity, by up-regulating the transcription of several angiogenic inducers, including VEGF-A." (PMID 22846499, 2012). "Parameters that showed a clear correlation with the identified tumor subtypes were: proportion of stroma in the tumors, mucinous histology, the extent of nuclear β-catenin staining, MSI and the V600E BRAF mutation." (PMID 22712570, 2012). "BRAF inhibitors have been developed that have quite dramatic effects on patients with mutant BRAF tumours." (PMID 22475322, 2012). "In our series, CDKN2A methylation positivity correlated with more frequent right-sided disease, mucinous histology, tumor grade as well as with MSI, BRAF mutation and with KRAS mutation in the MSI setting only." (PMID 22925370, 2012). "In particular, the BRAF inhibitors vemurafenib and GSK2118643 show evidence of clinical activity in a large proportion of patients whose tumours harbour BRAFV600E/K mutations." (PMID 22127285, 2012). "This is in accordance with previous work showing transient, partial tumour regression in BRAF mutant xenografted tumours with MEK1/2 inhibition." (PMID 23039341, 2012). "Of these 5 tumours with loss of the 12p12.1 locus, 2 tumours harboured a KRAS mutation, and one tumour had a BRAF mutation, suggesting that the mechanism of gene copy number loss is independent of the KRAS and BRAF mutation status." (PMID 22804917, 2012). "On this regard, survival from recurrence was markedly worse in BRAF-mutant tumours into the PETACC-3 trial and this observation was consistent with the previously reported poor prognosis of BRAF mutations in advanced (stage IV) CRCs." (PMID 22931052, 2012). "BRAF, can also be used as a tool for tumor prognostication based in the recent evidences and in clinical practice." (PMID 22654559, 2011). "PLX4032 (RO 5185426) is an ATP competitive, orally administered BRAF inhibitor (wt BRAF IC50 100 nM) with high selectivity for the mutant allele (BRAFV600E IC50 31 nM) and has shown selective tumour suppression in mutant BRAF cell lines and xenograft models." (PMID 21139585, 2011). "TTP in the group of patients with wt-KRAS and wt-BRAF tumours and in the group of patients with wt-KRAS and mt-BRAF tumours was 16 months (95% CI: 10.7- 21.2 months) and 12 months (95% CI: 4.0- 15.0 months), respectively." (PMID 22933967, 2011). "KRAS mutations were detected in 37 (33%), BRAF mutations in eight (7.2%) and PIK3CA mutations in 11 (9.8%, 8 in exon 9 and 3 in exon 20) primary tumours, respectively." (PMID 21283802, 2011). "It is proposed that in BRAF wild-type tumours BRAF signalling is usually inactivated via BRAF-induced autophosphorylation, but this self-inhibitory process is interrupted by selective BRAF inhibition." (PMID 21139585, 2011). "PLX-4720 selectively inhibits MEK1/2-ERK1/2 activation, cell proliferation and xenograph tumor growth using mutant BRAF expressing cell lines." (PMID 21917148, 2011). "Previous studies have reported that MSI, CIMP, BRAF mutation, PIK3CA mutation, and tumour LINE-1 hypomethylation are associated with prognosis and that lymphocytic infiltration is associated with many of these molecular variables." (PMID 22110523, 2011). "Tumours with any variation in codons 12, 13 or 61 of KRAS and in exon 15 of BRAF were classified as mutated." (PMID 21901162, 2011). "R0 resection was achieved in 38/176 patients (21.6 %), of whom 37 patients had wt-BRAF and only one had mt-BRAF tumour." (PMID 22933967, 2011).
tumor (continued). "We reviewed the records of 80 consecutive patients with mutBRAF advanced malignancies and 149 with wild-type (wt) BRAF (matched by tumor type) referred to the Clinical Center for Targeted Therapy and analyzed their outcome." (PMID 22039425, 2011). "The result suggests that a substantial number of primary tumours, labelled as BRAF-wild type by conventional direct sequencing, actually contain a small fraction of BRAFV600E cells." (PMID 21224857, 2011). "TTP and OS to the ≥2nd line cetuximab-containing treatment according to KRAS, BRAF, PIK3CA mutations status, PTEN protein expression, AREG and EREG mRNA expression and grade of skin rash in the KRAS WT patients′ population." (PMID 21283802, 2011). "Associations were examined between methylation status and clinicopathlogical features, including tumour MSI status, BRAF V600E mutation, and patient survival." (PMID 21587258, 2011). "BRAF operates downstream of the RAS proteins and has been shown to be mutated in several tumor types." (PMID 21533174, 2011). "Previous studies have reported that MSI, CIMP, BRAF mutation, PIK3CA mutation, and LINE-1 tumor hypomethylation were associated with CRC prognosis, and that lymphocytic infiltration is associated with many of these molecular variables." (PMID 24212797, 2011). "In accordance with these previous reports, in the current study we also observed that patients with tumours that harboured BRAF mutations had a significantly worse TTP and shorter OS compared to BRAF wt tumours." (PMID 21283802, 2011). "The difference in TTP between the patients with wt-KRAS and wt-BRAF tumours and the patients with wt-KRAS and mt-BRAF tumours was 4 months." (PMID 22933967, 2011). "The comparison of median OS of those two groups showed a statistically significant difference which was also accompanied with a better prognosis of patients with wt-KRAS and wt-BRAF tumour." (PMID 22933967, 2011). "We demonstrate that across tumor types, patients often concomitantly harbor PIK3CA mutations and RAS/BRAF mutations." (PMID 21829508, 2011). "The average tumor size at presentation for BRAF V600E-positive tumors was 2.2 cm compared to 2.0 cm for BRAF V600E-negative tumors." (PMID 21479234, 2011). "The aim of this study was to investigate the clinical relevance of BRAF V600E mutation status, cyclin D1 expression and MSI status of primary tumours of patients with mCRC treated with front-line 5FU-based chemotherapy." (PMID 20485284, 2010). "A highly unfavourable outcome in patients with KRAS and BRAF wild-type tumours with overexpression of TOPK was noted (P=0.018)." (PMID 19935791, 2010). "CIMP subgroups were compared for various clinicopathological and molecular features including patient age, tumor site, microsatellite instability (MSI), methylation at a consensus panel of CpG islands and mutations in BRAF and KRAS." (PMID 20492682, 2010). "Diffuse TOPK expression was observed in 19 (82.6%) KRAS wild-type and 21 (91.3%) BRAF wild-type tumours." (PMID 19935791, 2010). "In a recent study, MEK inhibitor CI-1040 has been found to abrogate tumor growth in BRAF mutant xenografts derived from various tumor types." (PMID 20628483, 2010). "These seven patients with tumor regression remained free of tumor progression for 4 to 14 months, as compared with two patients with BRAF wild-type who showed progressive disease." (PMID 24281076, 2010). "Tumour specimens from 48 metastatic CRC patients treated with cetuximab-based chemotherapy were evaluated for KRAS and BRAF mutational status and MKP-1 expression as assessed by immunohistochemistry." (PMID 20234366, 2010).
tumor (continued). "Mutations in BRAF (P=0.002) and KRAS (P=0.054) occurred more frequently in patients with diffuse TOPK staining compared with patients with wild-type tumours." (PMID 19935791, 2010). "Patients with MSI-H and BRAF-mutated tumours experienced significantly lower PFS (3.1 vs 11.4 months; P=0.008) and OS (14.5 vs 35.5 months; P=0.004) than patients with MSI-H and BRAF wt tumours." (PMID 20485284, 2010). "BRAF mutations were detected in 10 (out of 22, 45%) patients with MSI-H tumours compared with 2 (out of 122, 1.6%) in those with microsatellite stable tumours (P<0.001)." (PMID 20485284, 2010). "BRAF mutations were present in 45 and 1.6% of the patients with MSI-H and MSS tumours respectively (P<0.001)." (PMID 20485284, 2010). "Expression of cyclin D1 and Ki67 (all proteins located downstream of the BRAF kinase) were analyzed by immunohistochemistry in paired tumor biopsies (pre- and post treatment) from 15 of 36 patients." (PMID 21206909, 2010). "The results of this study show that patients with BRAF-mutated tumours had a significantly lower median PFS and OS compared with patients with wt tumours." (PMID 20485284, 2010). "Downstream of KRAS in ERK/MAPK signalling lies BRAF, a gene that in sporadic disease is mutated in ∼10% of CRC and is more highly associated with tumours showing microsatellite instability (MSI)." (PMID 19935791, 2010). "Supervised clustering analysis with Bonferroni correction revealed that only 1 of the 202 tumor-specific CpG sites was differentially methylated between these tumor groups (HTR1B_P222_F, upregulated in BRAF mutant tumors, p = 8.1 × 10-6)." (PMID 20492682, 2010). "It has been reported that a large majority (43–87%) of MSI-H sporadic tumours have BRAF mutations, whereas only a small proportion (4–9%) of MSS tumours have BRAF mutations." (PMID 20051945, 2010). "In vivo, combined CRAF and BRAF knock-down showed a significant delay in tumor growth compared to the un-induced control." (PMID 19492075, 2009). "We determined KRAS, BRAF and PIK3CA mutations in tumours from 168 patients treated for mCRC at two institutions." (PMID 19603024, 2009). "Serum-derived cfDNA was BRAF+ in 33 of 126 (26.2%) samples, including in five samples for which tumour data were unavailable." (PMID 19861964, 2009). "Of the 96 tumour samples available from patients with cfDNA data, 45 (47%) were detected to be BRAF+ by ARMS." (PMID 19861964, 2009). "We retrospectively analyzed objective tumor response, progression-free (PFS) and overall survival (OS) together with the mutational status of KRAS, BRAF, PIK3CA and expression of PTEN in 132 tumors from cetuximab or panitumumab treated mCRC patients." (PMID 19806185, 2009). "A high CD8+ index was associated with significantly more frequent peritumoural lymphocytic inflammation at the tumour front (P=0.002), with MSI-H status (P=0.033) and marginally with BRAF mutation." (PMID 19755986, 2009). "All KRAS, BRAF, and EGFR mutations were mutually exclusive across different tumor types while some PIK3CA mutant cases also harbored one of the other three mutations." (PMID 19826477, 2009). "In contrast, patients with BRAF-mutant tumours had significantly lower PFS (median 4.3 vs 12.5 months; P<0.0001) compared with patients whose primary tumours carried only wild-type (WT) BRAF alleles." (PMID 19603024, 2009). "We determined with confidence the mutational status for KRAS exon 2, BRAF exon 15, and PIK3CA exons 9 and 20 in 168 consecutive patients with mCRC, for whom a representative sample from the primary tumour was available for molecular analysis of DNA." (PMID 19603024, 2009). "BRAF status by tumour sample (in the primary analysis of 200 patients) or cfDNA (n=126) was not shown to be a prognostic factor for PFS (data not shown)." (PMID 19861964, 2009). "KRAS mutations were detected in 62 (37%), BRAF mutations in 13 (8%) and PIK3CA mutations in 26 (15%, 18 in exon 9 and 8 in exon 20) primary tumours, respectively." (PMID 19603024, 2009).